CRP (C-reactive protein)
Diseases named in the same sentence as CRP in open-access papers (continued):
Sharing a sentence is not in itself a finding about the gene and the disease.
periodontal disease (continued). "Numerous studies show that patients with periodontal disease have elevated levels of systemic inflammatory mediators compared to healthy controls, including C-reactive protein (CRP), interleukin 1 (IL-1), interleukin 6 (IL-6), and tumor necrosis factor-α (TNF-α)." (PMID 40026941, 2025). "Furthermore, several acute-phase proteins, such as CRP, present significantly elevated levels in the serum of patients with periodontal disease compared with control individuals." (PMID 40872734, 2025). "However, a previous study reported that increased CRP levels and white blood cell counts occurred during active periods of periodontal disease." (PMID 40552326, 2025). "For instance, elevated CRP levels may indicate systemic inflammation from periodontal disease, but they can also be influenced by unrelated conditions such as obesity or acute infections." (PMID 40418274, 2025). "Similarly, researchers have shown that levels of C-reactive protein (CRP), an indicator of systemic inflammation, significantly increase in the serum of patients affected by periodontal disease." (PMID 40231144, 2025). "While previous studies did not incorporate CRP or other systemic and oral health-related factors into their analyses, the current study demonstrated that reduced eGFR, in conjunction with elevated CRP, serves as a significant predictor of periodontal disease within a robust methodological framework." (PMID 39859455, 2025). "The findings suggest that salivary MIP-1α, CRP, and Adiponectin could potentially serve as a discriminatory tool for evaluating and assessing various stages of periodontal disease." (PMID 38433948, 2024). "CRP can be an objective indicator of disease activity in patients with periodontal disease." (PMID 37575815, 2023). "Treatment of periodontal disease has shown a reduction in the hs-CRP level." (PMID 35994451, 2022). "All women presented moderate CVR, without an evident association between serum hs-CRP levels and periodontal diseases." (PMID 34439905, 2021). "All women had moderate cardiovascular risk, without an evident association between serum hs-CRP levels and periodontal diseases." (PMID 34439905, 2021). "Based on the results of this study, the burden of milder forms of periodontal disease over serum CRP levels from high BMI individuals is probably irrelevant, which could be a interesting finding to consider, and opens a field for future studies." (PMID 34439905, 2021). "Linear regression was used to examine the association between plasma 25-hydroxyvitamin D (25[OH]D) concentrations, a biomarker of vitamin D status, and both salivary and serum CRP concentrations in 567 women from the Buffalo Osteoporosis and Periodontal Disease (OsteoPerio) Study (1997–2000)." (PMID 33807159, 2021). "Further studies are needed to compare the CRP levels of men and women with periodontal disease." (PMID 33424972, 2020). "Salivary CRP levels may be elevated in patients with periodontal diseases, which emphasizes the need to consider oral health in following studies." (PMID 33488610, 2020). "As the increase in age was not a direct cause of periodontal disease, it was considered that the increase in the age of periodontal disease does not increase the CRP concentration together." (PMID 33424972, 2020). "Furthermore, intervention studies have shown that treatment of periodontal disease decreased systemic levels of IL-6 and CRP." (PMID 31382656, 2019). "Thus, there are contrasting opinions regarding the pathological significance of serum CRP levels in HD patients with periodontal disease." (PMID 31382656, 2019). "Furthermore, other investigators have shown that serum CRP levels were decreased following periodontal therapy (p = 0.001) in HD patients with periodontal disease." (PMID 31382656, 2019).
periodontal disease (continued). "In addition, periodontal disease increases the number of blood leukocytes and systemic levels of pro-inflammatory mediators, such as C-reactive protein, soluble cellular adhesion molecules, and fibrinogen, which are produced in response to cellular damage." (PMID 31029089, 2019). "The main source of the increase levels of CRP in saliva could be crevicular fluid, due to the greater incidence of periodontal disease observed in these patients." (PMID 30043213, 2018). "It is possible to use CRP in prediction and early detection of periodontal disease." (PMID 26346216, 2015). "Nevertheless, we have to realize that for certain cases, even with high levels of CRP, other factors might play a more dominant role in the onset and/or progression of periodontal disease." (PMID 26348353, 2015). "CRP can be used for the prediction and early detection of periodontal disease." (PMID 26346216, 2015). "CRP can also be used for the prediction and early detection of periodontal disease." (PMID 24551806, 2013). "In addition, periodontal disease patients with CKD indicators had a higher percentage of high of CRP (≥1.03 mg/L), high TNF-α (≥1.12 ng/L) and high IL-6 (≥7.54 ng/L) levels than those without indictors of kidney damage." (PMID 23951003, 2013). "These high CRP levels could be involved in the development of diabetic complications and periodontal disease progression and reduction of these values should be a medical goal in these patients." (PMID 22322513, 2012). "These cytokines are involved in periodontal destruction and initiate acute response that includes protein liberation such as C-Reactive Protein (CRP), whose elevation has been identified as a common element to periodontal disease and to cardiovascular diseases." (PMID 28348657, 2011). "A link between periodontal pathogens and CRP hasa been observed in relation to periodontal disease." (PMID 23019501, 2011). "Unrecognized infections such as periodontal disease may induce acute-phase response, elevating CRP levels." (PMID 21219642, 2011). "Significantly elevated CRP levels were found in subjects with periodontal disease." (PMID 20379412, 2009). "Therefore, inflammation from periodontal disease could contribute to the progression of CKD by increasing levels of inflammatory markers like CRP." (PMID 40715391, 2025). "This correlation may be attributed to inflammatory and immunological responses common to both periodontal disease and systemic diseases, leading to an increase in circulating inflammatory cytokines, such as C-reactive protein (CRP), interleukin (IL)-6, and tumor necrosis factor (TNF)-α." (PMID 38132221, 2023). "Whereas there are many patients that a lot of residual teeth have a good mouth cleaning state in Eichner A. Also, Eichner C has few residual teeth and does not reach it before we greatly change CRP even if periodontal disease is severe because there are few teeth causing inflammation." (PMID 35356942, 2022). "Deepening the links between periodontal diseases and C-reactive protein could contribute to the subsequent prevention and control of prevalent inflammatory diseases, placing special emphasis on timely periodontal care that may positively influence public health." (PMID 34439905, 2021). "Additionally, periodontal disease treatments reduce the levels of IL-6, CRP, etc.33–36." (PMID 34262126, 2021). "Periodontal diseases being inflammatory pathologies, they induce the production of inflammatory mediators such as tumor necrosis factor α (TNF-α), interleukins (IL-1, IL-6, IL-8) and the C-reactive protein (CRP) that have been shown to be associated with atherogenesis." (PMID 33575410, 2021). "However, simple measurement and classification of periodontal status did not reveal a clear association between periodontal disease and cognitive function or CRP." (PMID 29304177, 2018).
periodontal disease (continued). "Although the periodontal disease status of our patient population is unknown, C-reactive protein (CRP) levels recorded for 17/42 patients ranged from 27 to 91 mg/L, which could possibly correlate with periodontal disease in patients with cardiovascular disease." (PMID 28326156, 2017). "Furthermore, the model presented may elucidate important CHD biomarkers which should be measured in patients with periodontal disease to more adequately screen for CHD risk, namely HOMA, TNF-α, CRP, IL-6, GDF-15, OPG, MPO and fibrinogen." (PMID 27846870, 2016). "Biological plausibility for considering periodontal disease as a CKD risk factor is derived from the potential role of the inflammatory response to periodontal disease in the chronic systemic inflammatory burden (for example, increased C-reactive protein (CRP) levels) associated with CKD." (PMID 26520140, 2015). "Therefore elevation of CRP & TNF-α such as that seen in periodontal disease may supplement systemic vascular inflammation, atheroma formation and add to the pre existing risk for cardiovascular sequelae." (PMID 24198887, 2013). "However, when either serum IL-6 or CRP was added to the model, severe periodontal disease was no longer significantly associated." (PMID 23950871, 2013). "C-reactive protein (CRP) is the most significant inflammatory marker involved in both cardiovascular and periodontal diseases." (PMID 40362598, 2025). "Rapid point-of-care (POC) tests, such as those measuring C-reactive protein (CRP) levels, have demonstrated potential in systemic inflammatory conditions and periodontal diseases." (PMID 40410141, 2025). "Most of the studies exploring CRP, IL-6, and TNF-α in CVD patients with periodontal disease were observational cohort or case–control designs." (PMID 41294894, 2025). "We found a positive statistical correlation between MIP-1α and CRP levels in the periodontal status of groups 2 and 3, consistent with other studies that used GCF, saliva, and serum to correlate periodontal disease with clinical parameters." (PMID 38433948, 2024). "Periodontal disease induces chronic inflammation, releasing pro-inflammatory cytokines like IL-6, TNF-α, and CRP, which exacerbate neuroinflammation, disrupt the blood–brain barrier, and promote neurodegeneration." (PMID 39768299, 2024). "Numerous pieces of research have shown that inflammatory cytokines like tumor necrosis factor alpha (TNF-α), C-reactive protein (CRP), and interleukin-6 play a role in the connection between PCOS and periodontal disorders." (PMID 38021744, 2023). "Elevations of pro-inflammatory mediators, such as IL-1, IL-6, C-reactive protein (CRP), and fibrinogen, as well as increased neutrophil count in the blood, have been observed in individuals with periodontal disease." (PMID 37513004, 2023). "The increased salivary CRP at levels reported in previous studies may serve as a plausible indicator of the inflammatory status of the medwakh smokers since we have excluded the effects of reported periodontal diseases among the study subjects as described in the exclusion criteria." (PMID 36725974, 2023). "Therefore, this study did not prove any significant relationship between elevated CRP levels and periodontal disease and observed that early tooth loss resulting from an oral infection was the possible cause of levels higher than 10 mg/L in edentulous patients." (PMID 35225864, 2022). "On the other hand, biomarkers of periodontal disease progression in GCF alone (MMP-8, MMP-9, Osteoprotegerin, C-reactive Protein and IL-1β) provided low sensitivity and high specificity values of 23% and 95%, respectively." (PMID 31817894, 2019). "Periodontal probing depth, a well-known marker of periodontal disease, correlates with the duration of SLE, the accumulated dose of prednisone, and serum C-reactive protein (CRP) levels." (PMID 30585183, 2018). "Therefore, IL-6 levels may correlate less with periodontal disease than CRP or orosomucoid." (PMID 23526947, 2013).
periodontal disease (continued). "We compared the CRP levels between two groups: the group of subjects who underwent periodontal treatment and the patients who did not receive periodontal disease treatment." (PMID 40272186, 2025). "Treating periodontal disease reduces pro-inflammatory mediator levels such as IL-6, tumor necrosis factor-α (TNF-α), CRP, and reactive oxygen species (ROS) and increases pro-resolving lipid mediators, which are anti-inflammatory in nature and help maintain homeostasis." (PMID 40916006, 2025). "Evidence consistently links severe periodontal disease with elevated CRP levels, which contribute to the progress of other non-communicable diseases." (PMID 39859455, 2025). "Compared with healthy individuals, patients with periodontal disease have significantly higher blood levels of inflammatory cytokines, which are derived from the endotoxins of gram-negative bacteria, and C-reactive protein (CRP)." (PMID 39150920, 2024). "In contrast, other studies of patients with inflammatory bowel disease in Germany or periodontal disease in the United States found a stable concentration of 25(OH)D regardless of the presence of elevated CRP." (PMID 36789936, 2023). "Hs-CRP is not a marker specific to periodontal disease; however, it is a highly sensitive marker suited to measuring periodontal disease, which is regarded as a mild chronic inflammation." (PMID 35805792, 2022). "Also, C-reactive proteins (CRP), IL-12, MMP-8, MMP-9, and MMP-13 have been described as biomarkers for the periodontal disease." (PMID 35368315, 2022). "Periodontal disease severity was classified into nine groups by combining ABL and hs-CRP." (PMID 35805792, 2022). "Although CRP is a non-specific marker of inflammation, studies suggest that CRP is elevated in periodontal diseases, which further complicates the health status of the patient with CHD." (PMID 35845078, 2022). "This is particularly important because CRP has been shown to be elevated in individuals with periodontal disease and no systemic disease." (PMID 35993013, 2022). "However, potential factors include the mediators derived from periodontal disease (Interleukin (IL)-6 tumour necrosis factor (TNF)-α, and C-reactive protein (CRP) as well as oxygen radical) which impair insulin signalling and resistance." (PMID 33810479, 2021). "This fact suggests that CRP in GCF might be indicative of systemic inflammation, either generated at distant organs and/or induced by periodontal disease." (PMID 34439905, 2021). "This non-significant relationship between serum CRP levels and severity of periodontal disease was supported by other investigators." (PMID 31382656, 2019). "One study found elevations of CRP levels in the order of 30% when compared to patients without periodontal disease." (PMID 27846870, 2016). "Numerous studies have noted increased serum levels of CRP in patients with periodontal disease compared to those without." (PMID 27846870, 2016). "Moreover, it was confirmed that the severity of the periodontal disease and the serum levels TNF-α, IL-6 and CRP were significantly correlated." (PMID 26644840, 2015). "In this study, an attempt was made to evaluate the CRP levels in pregnant women with and without periodontal disease and healthy control using ultrasensitive measurement of CRP, with a detection limit of 0.015 mg/dl." (PMID 20379412, 2009). "Therefore, treating periodontal disease not only reduces pro-inflammatory mediators such as IL-6, tumor necrosis factor-α (TNF-α), CRP, and reactive oxygen species (ROS), but also increases the levels of pro-resolving lipid mediators, which are crucial for maintaining homeostasis." (PMID 40916006, 2025). "Inflammatory reactions represented by vascular access infection, biocompatibility of dialysis procedures, back-filtration of nonsterile dialysate and periodontal disease can initially influence CRP with a subsequent affliction of the muscle mass and nutritional indices." (PMID 37239661, 2023).
periodontal disease (continued). "We did not consider other factors that may be related to periodontal disease and MS, such as socioeconomic status, inflammation indices (e.g. CRP) or psychosocial factors." (PMID 23829196, 2013). "We have to consider that CRP is a nonspecific marker of the acute-phase response, and according to that, periodontal disease but also other potential stimuli such as unknown chronic infections or inflammatory conditions may produce mild CRP increases." (PMID 22322513, 2012). "In contrast to NLR, procalcitonin, CRP, neutrophil count, lymphocyte count, and other markers, DNI is a new biomarker with which many clinicians are not familiar due to its lack of research in periodontal diseases." (PMID 35319605, 2022).